CFAP126 (cilia and flagella associated protein 126)
Description:
Microtubule inner protein (MIP) part of the dynein-decorated doublet microtubules (DMTs) in cilia axoneme. Acts as a regulator of cilium basal body docking and positioning in mono- and multiciliated cells (By similarity). Regulates basal body docking and cilia formation in multiciliated lung cells (By similarity). Regulates kinocilium positioning and stereocilia bundle morphogenesis in the inner ear (By similarity).
Synonyms: C1orf192; FLTP; Flattop
Tractability: Small molecule: a structure with a bound ligand is known. Antibody: its Gene Ontology location is reachable by antibodies, with high confidence; UniProt places it where antibodies can reach, with medium confidence.
Gene: Protein-coding gene on chromosome 1 (161,364,733 to 161,367,885, reverse strand). Ensembl gene ENSG00000188931.
Subcellular location: Cytoplasm, cytoskeleton, cilium basal body; Cell projection, cilium; Apical cell membrane; Cytoplasm, cytoskeleton, cilium axoneme; Cytoplasm, cytoskeleton, flagellum axoneme
Subcellular location (Human Protein Atlas): Mid piece; Plasma membrane; Primary cilium; Cytosol; Principal piece; Vesicles
Gene Ontology:
Biological process: cilium organization; flagellated sperm motility
Cellular component: axonemal microtubule; cilium; apical plasma membrane; axonemal B tubule inner sheath; ciliary basal body; sperm flagellum; axoneme
Genetic constraint (gnomAD): Loss-of-function variants: 21 observed, 18.94 expected, observed/expected ratio (o/e) 1.11, 90% interval 0.79 to 1.59. The upper end of that interval is the gene's LOEUF score, 1.59, which puts it in group 6 of 6, group 1 being the genes least tolerant of losing a copy. Missense variants: 174 observed, 225.4 expected, observed/expected ratio (o/e) 0.77, 90% interval 0.68 to 0.88. Synonymous variants: 65 observed, 77.96 expected, observed/expected ratio (o/e) 0.83, 90% interval 0.68 to 1.02.
Homologues: Orthologues: chimpanzee CFAP126 (99% identical), macaque CFAP126 (95% identical), dog CFAP126 (87% identical), rabbit CFAP126 (86% identical), pig CFAP126 (85% identical), rat Cfap126 (76% identical), mouse Cfap126 (74% identical), tropical clawed frog CFAP126 (46% identical), zebrafish cfap126 (33% identical), Drosophila melanogaster CG3062 (20% identical).
Diseases named in the same sentence as CFAP126 in open-access papers:
CFAP126 is named in the same sentence as 4 diseases in open-access papers, as found by Europe PMC text mining. Sharing a sentence is not in itself a finding about the gene and the disease. The quoted sentences say what the papers report.
ovarian carcinoma (1 paper, 2025). A malignant neoplasm originating from the surface ovarian epithelium. "C2 SLC40A1+ TCs and C5 CFAP126+ TCs, characterized by a significant prevalence in ovarian cancer tissues, demonstrated a low degree of differentiation, suggesting a higher malignancy in these two subtypes of TCs." (PMID 40612060, 2025).
CFAP126 also shares sentences with these, for which no sentence is quoted: ependymoma (1 paper); lung disease (1); tumor (1).